ARHGAP11A (Rho GTPase activating protein 11A)
Description:
GTPase activator for the Rho-type GTPases by converting them to an inactive GDP-bound state.
Synonyms: KIAA0013; GAP (1-12)
Tractability: Small molecule: it has a binding pocket of medium quality. PROTAC: ubiquitination databases record sites on it.
Gene: Protein-coding gene on chromosome 15 (32,615,144 to 32,639,952, forward strand). Ensembl gene ENSG00000198826.
Subcellular location: Nucleus
Subcellular location (Human Protein Atlas): Cytosol; Nucleoli
Pathways (Reactome):
Signal Transduction: RHOA GTPase cycle
Gene Ontology:
Molecular function: GTPase activator activity
Biological process: positive regulation of GTPase activity; regulation of small GTPase mediated signal transduction; signal transduction
Cellular component: nucleus; cytosol
Genetic constraint (gnomAD): Loss-of-function variants: 33 observed, 55.16 expected, observed/expected ratio (o/e) 0.6, 90% interval 0.45 to 0.8. The upper end of that interval is the gene's LOEUF score, 0.8, which puts it in group 3 of 6, group 1 being the genes least tolerant of losing a copy. Missense variants: 1,043 observed, 1,195.2 expected, observed/expected ratio (o/e) 0.87, 90% interval 0.83 to 0.92. Synonymous variants: 355 observed, 416.62 expected, observed/expected ratio (o/e) 0.85, 90% interval 0.78 to 0.93.
Homologues: Orthologues: chimpanzee ARHGAP11A (99% identical), macaque ARHGAP11A (94% identical), rabbit ARHGAP11A (79% identical), rat Arhgap11a (69% identical), mouse Arhgap11a (68% identical), tropical clawed frog arhgap11a (39% identical), zebrafish arhgap11a (34% identical), Caenorhabditis elegans rga-3 (14% identical), Caenorhabditis elegans rga-4 (13% identical). Paralogues in human: ARHGAP11B (23% identical).
Diseases named in the same sentence as ARHGAP11A in open-access papers:
ARHGAP11A is named in the same sentence as 36 diseases in open-access papers, as found by Europe PMC text mining. Sharing a sentence is not in itself a finding about the gene and the disease. The quoted sentences say what the papers report.
breast carcinoma (10 papers, 2013 to 2024). "RACGAP1 inhibits cell migration in Basal-like Breast Cancer cell lines, while ARHGAP11A promotes it42." (PMID 32728097, 2020). "ARHGAP11A codes for a Rho GTPase‐activating protein that enhances invasiveness in colon and breast cancer." (PMID 26992833, 2016). "In previous studies, ARHGAP11A was found to promote the development of basal breast cancer, colon cancer, hepatoma, and gastric cancer by accelerating cell transition from the G1 to S phase, inactivating Rac1B or regulating the TPM1-mediated actin filament stability." (PMID 37175461, 2023). "Notably, depletion of ARHGAP11A in basal-like breast cancer cells was shown to lead to cell-cycle arrest mediated by p27 while depletion of RacGAP1 led to an increase in p21 protein associated with an increase in senescence." (PMID 34493786, 2021). "The results showed that ARHGAP11A was highly expressed in lung cancer, breast cancer, pancreatic cancer, esophageal cancer, gastric cancer, and other types of cancers and that the mRNA expression level of ARHGAP11A was higher in gastric cancer tissues than in adjacent normal tissues." (PMID 34912455, 2021). "Moreover, ARHGAP11A was up-regulated in various cancer tissues other than colorectal cancers, including glioblastoma, lung cancer, breast cancer, gastric cancer, hepatocellular carcinoma and pancreatic cancers." (PMID 24386239, 2013). "In our study, using the Kaplan-Meier plotter, we also investigated the correlation between the expression of ARHGAP11A and ARHGAP11B and OS possibility in different types of breast cancer." (PMID 38046902, 2023). "LncRNA and piRNA were reported to upregulate ARHGAP11A level in human hepatocellular carcinoma (HCC) and breast cancer." (PMID 37175461, 2023). "This variant resulted in enhanced invasiveness when transfected into the breast cancer cell line MCF7, in part attributed to altered DNA methylation patterns of the ARHGAP11A gene leading to increased expression levels." (PMID 26992833, 2016). "In the current study, we analyzed the expression levels of two RhoGAP genes, ARHGAP11A and ARHGAP11B, in The Cancer Genome Atlas (TCGA) breast cancer (BRCA) and also our 51 IDC tumors compared to their matched normal tissues using quantitative polymerase chain reaction (qPCR)." (PMID 38046902, 2023). "In basal-like breast cancer cells, ARHGAP11A has oncogenic rather than tumor-suppressive effects and is an ideal target for the treatment of invasive tumors." (PMID 34912455, 2021). "The piR-021285 variant mimics transfection into breast cancer cell lines and weakens pro-invasive and pro-apoptosis gene methylation of ARHGAP11A at the 5′-UTR-first exon CpG site, which results in higher ARHGAP11A expression and increased breast cancer cell invasiveness." (PMID 33718365, 2021).
gastric cancer (10 papers, 2013 to 2024). A primary or metastatic malignant neoplasm involving the stomach. "For instance, miR-30c-2-3p, associated with gastric cancer, can suppress malignant progression by inhibiting ARHGAP11A." (PMID 39732166, 2024). "The evaluation of immune infiltrates in gastric cancer showed that ARHGAP11A expression was significantly associated CD8+ T cells, CD4+ T cells, macrophages and dendritic cells." (PMID 34733886, 2021). "Results revealed that high expression of ARHGAP11A was significantly associated with a better prognosis in gastric cancer (OS HR = 0.7, p = 6.4e−04) and blood cancer (The cohort GSE12417, OS HR = 0.47, Cox p = 0.047)." (PMID 34733886, 2021). "We found that high expression of ARHGAP11A, a representative gene with mutation characteristics in the clonal evolution of gastric cancer metastasis, appeared more frequently in gastric cancer with lymph node metastasis (unpublished data)." (PMID 34733886, 2021). "Among 1,120 gastric cancer patients, ARHGAP11A was changed in 22 samples (2%), including 13 mutations, 5 amplifications and 4 deep deletions." (PMID 34733886, 2021). "ARHGAP11A facilitates the malignant advancement of gastric cancer by modulating actin filament stability via TPM124." (PMID 38783033, 2024). "Surprisingly, high ARHGAP11A level was also reported to correlate with better prognosis in gastric cancer patients due to the detrimental effects on the suppressive TIME, which is inconsistent with its gastric cancer-promoting role." (PMID 37175461, 2023). "Several studies revealed that, in addition to various types of BCs, especially BLBCs, ARHGAP11A has a high expression level in human glioblastoma, colon, lung, hepatocellular, and gastric cancers." (PMID 38046902, 2023). "Nevertheless, the prognostic significance of ARHGAP11A and its correlation with immune infiltrates including TILs in gastric cancer is obscure." (PMID 34733886, 2021). "We consequently explored the correlation between ARHGAP11A expression and immune infiltrates in gastric cancer." (PMID 34733886, 2021). "In our ongoing parallel study, high expression of ARHGAP11A appeared more frequently in gastric cancer with lymph node metastasis." (PMID 34733886, 2021). "For example, the M1 Macrophage marker NOS2 and the dendritic cell marker, HLA-DPB1 and CD1C, were significantly correlated with ARHGAP11A expression in gastric cancer." (PMID 34733886, 2021). "On the other hand, the detailed mechanisms of ARHGAP11A in regulating gastric cancer metastasis needs further study." (PMID 34733886, 2021). "We used wound-healing assays to evaluate the cell migration ability, and the results showed that ARHGAP11A overexpression promoted the migration ability of gastric cancer cells compared with that of the WT cells." (PMID 34912455, 2021). "Further studies revealed that ARHGAP11A promotes the malignant progression of gastric cancer cells by interacting with TPM1 to affect cell migration and invasion and the stability of actin filaments." (PMID 34912455, 2021). "We further evaluated the relationship between ARHGAP11A expression and these immune markers in gastric cancer using the GEPIA." (PMID 34733886, 2021). "In this study, we found that the expression of ARHGAP11A is positively correlated with a low degree of tumor differentiation and low survival rate of human gastric cancer patients." (PMID 34912455, 2021). "In summary, our research reveals the promoting role of ARHGAP11A in the malignant development of gastric cancer and identifies the mechanism by which ARHGAP11A plays its role." (PMID 34912455, 2021). "Studies have shown that ARHGAP11A plays a crucial role in the maintenance of gastric cancer stem cells." (PMID 34912455, 2021). "Another researchers identified 17 highly expressed key genes in gastric cancer tissues by weighted gene coexpression network analysis, and ARHGAP11A is one of them." (PMID 34912455, 2021).
gastric cancer (continued). "We next analyzed the correlation between ARHGAP11A expression and immune infiltrates in gastric cancer by using TIMER." (PMID 34733886, 2021). "The mRNA expression level of ARHGAP11A was higher in gastric cancer tissues than in adjacent normal tissues." (PMID 34912455, 2021). "Silencing ARHGAP11A in vitro, resulting in the decrease of the invasive ability of gastric cancer cells to lymphatic endothelial cells (unpublished data)." (PMID 34733886, 2021). "As an oncogene in gastric cancer, ARHGAP11A is dependent on TPM1 to regulate cell stress fiber formation and stability and promote gastric cancer cell proliferation, invasion, and migration, thus promoting gastric cancer progression." (PMID 34912455, 2021). "First, we performed gene expression profile analysis on 16 pairs of gastric cancer and normal tissues and found that ARHGAP11A, a member of the RhoGAP family, showed a signficantly increased expression." (PMID 34912455, 2021). "To further understand the role of ARHGAP11A in gastric cancer, we analyzed the correlation between the ARHGAP11A expression and clinical parameters by using the Kaplan-Meier plotter." (PMID 34733886, 2021). "The results showed that ARHGAP11A, in the Rho GTPases-activating protein family, exhibited significantly increased expression in gastric cancer tissues." (PMID 34912455, 2021). "The expression of ARHGAP11A was increased in gastric cancer cells and tissues, and high ARHGAP11A expression in tissues was related to the degree of tumor differentiation and poor prognosis." (PMID 34912455, 2021). "High expression of ARHGAP11A was significantly correlated with a better prognosis in gastric cancer." (PMID 34733886, 2021). "In this study, we found that ARHGAP11A is the most highly expressed gene of the Rho GTPase-activating protein family in gastric cancer." (PMID 34912455, 2021). "In summary, TPM1 is an interacting protein of ARHGAP11A that plays a key role in the ARHGAP11A-induced malignant progression of gastric cancer." (PMID 34912455, 2021). "In this study, the effect of ARHGAP11A on the occurrence and development of gastric cancer and the mechanism related to this effect were studied." (PMID 34912455, 2021). "The important role of ARHGAP11A in gastric cancer provides us with a new potential therapeutic target for the study of gastric cancer." (PMID 34912455, 2021). "Further in vivo and in vitro analyses confirmed that the role of ARHGAP11A in gastric cancer cells is to promote cell proliferation, migration, and invasion." (PMID 34912455, 2021). "ARHGAP11A, a prognostic biomarker, is correlated with immune infiltrates in gastric cancer." (PMID 36185204, 2022). "In addition, high ARHGAP11A expression significantly correlated with a better prognosis in gastric cancer." (PMID 36185204, 2022). "Interestingly, an interaction effect exists between ARHGAP11A expression and therapeutic strategy on the prognosis of gastric cancer." (PMID 34733886, 2021). "Moreover, ARHGAP11A knockout significantly inhibited cell proliferation, cell migration, and invasion in vitro and significantly inhibited the tumorigenic ability of gastric cancer cells in nude mice in vivo." (PMID 34912455, 2021). "Cell migration is powered by the continuous contraction of stress fibers and the growth and extension of actin filaments; thus, we further studied whether ARHGAP11A can induce stress fiber changes in gastric cancer cells." (PMID 34912455, 2021). "The upper results implied ARHGAP11A might affect patient prognosis via regulating immune infiltrates in gastric cancer." (PMID 34733886, 2021). "In summary, ARHGAP11A might be a crucial regulator of immune infiltrates and a valuable prognostic marker in patients with gastric cancer." (PMID 34733886, 2021). "Correlation of ARHGAP11A and clinical parameters in gastric cancer from Kaplan-Meier Plotter." (PMID 34733886, 2021). "In our study, genetic alterations of ARHGAP11A were identified in 2% of gastric cancer." (PMID 34733886, 2021).
gastric cancer (continued). "In addition, the proliferation ability of gastric cancer cells was evaluated by an EdU incorporation assay, and it was found that the proliferation of gastric cancer cells slowed down after ARHGAP11A knockout." (PMID 34912455, 2021). "Although the regulatory mechanisms controlling GID4-mediated ARHGAP11A degradation under physiological conditions remain to be examined, we note that ARHGAP11A expression is increased in various cancers, including hepatocellular and clear cell renal carcinoma and gastric cancer." (PMID 39389782, 2024). "Thus, we concluded that ARHGAP11A can promote the proliferation of gastric cancer cells." (PMID 34912455, 2021). "However, the role of ARHGAP11A in gastric cancer is obscure." (PMID 34733886, 2021). "ARHGAP11A might involve in the T cell infiltration of gastric cancer." (PMID 34733886, 2021). "Therefore, we inferred that ARHGAP11A is closely related to the progression of gastric cancer." (PMID 34912455, 2021). "ARHGAP11A might play a key role in lymph node metastasis of gastric cancer." (PMID 34733886, 2021). "In addition, ARHGAP11A mutations did not affect the prognosis of gastric cancer." (PMID 34733886, 2021). "After successfully constructing ARHGAP11A knockout cell lines in AGS, MKN45, and HGC27 cells using the KO1 target, we studied the effect of this gene on the proliferation of gastric cancer cells." (PMID 34912455, 2021). "Our study showed that ARHGAP11A can interact with TPM1 in gastric cancer cells, thereby promoting gastric cancer progression by affecting the formation and stability of the actin filaments." (PMID 34912455, 2021). "ARHGAP11A is related to the infiltration of immune cells (CD8+ T cells, CD4+ T cells, macrophages, and dendritic cells) in gastric cancer and may be an important regulator of immune infiltrating cells and a valuable prognostic marker." (PMID 34912455, 2021). "ARHGAP11A, in the Rho GTPase activating protein family, is highly expressed in gastric cancer, but its function and mechanism have not yet been explored." (PMID 34912455, 2021). "ARHGAP11A is a member of the Rho GTPase-activating protein family, but its role in gastric cancer has not been elucidated, and the related mechanisms have not been thoroughly explored." (PMID 34912455, 2021).
hepatocellular carcinoma (8 papers, 2013 to 2023). A malignant tumor that arises from hepatocytes. "Finally, in hepatocellular carcinoma (HCC), the GAP Rho GTPase-activating protein 11A (ARHGAP11A) has been shown by coimmunoprecipitation assay to directly interact with RAC1B independent of Rho GTPase-activating activity and to promote the HCC malignant phenotype." (PMID 30621237, 2019).
colon cancer (5 papers, 2013 to 2023). "Histological analyses of surgically dissected human colon cancer samples showed the preferential expression of ARHGAP11A at invasion sites, an expression pattern resembling that of GMNN." (PMID 24386239, 2013). "Interestingly, ARHGAP11A expression induced an increase in the relative Rac1 activity by blocking RhoA signaling, which led to an increase in the invasion ability of colon cancer cells." (PMID 33126743, 2020). "Additionally, analysis of human specimens showed the significant up-regulation of Arhgap11a in colon cancers, which was correlated with clinical invasion status." (PMID 24386239, 2013). "Next, we investigated the clinical relevance of ARHGAP11A in human colon cancers in situ." (PMID 24386239, 2013).
glioma (5 papers, 2018 to 2024). A benign or malignant brain and spinal cord tumor that arises from glial cells (astrocytes, oligodendrocytes, ependymal cells). "While in gliomas, ARHGAP11A played a tumor-suppressing role by inducing cell-cycle arrest and apoptosis." (PMID 37175461, 2023). "This does not mean that DRP2, IGFBP5, KLF10, ARHGAP11A and NRP2 are not essential genes for glioma pathogenesis, given the missing data and limited sample size we found." (PMID 34434651, 2021). "Two (ARHGAP11A, NRP2) of them showed no big difference between normal and glioma samples." (PMID 34434651, 2021). "Among them, ARHGAP11A, DRP2, HNRNPA3, KLF10, PAIP1, and RCN1 have not yet been studied in gliomas." (PMID 34434651, 2021).
colorectal cancer (4 papers, 2013 to 2022). A primary or metastatic malignant neoplasm that affects the colon or rectum. "We re-analyzed microarray data deposited in the NCBI Gene Expression Omnibus (GEO) database using the NextBio data mining framework and found that ARHGAP11A was up-regulated in colorectal cancer tissues in eight of ten datasets." (PMID 24386239, 2013). "For example, linc01207 regulates ARHGAP11A and promotes the progression of non-small cell lung cancer by secreting mir-525-5p; long noncoding RNA, SNHG10, promotes the malignant progression of colorectal cancer cells by targeting mir-3690." (PMID 35647035, 2022). "We also analyzed the expression of ARHGAP11A in clinical samples, including 74 colorectal cancers and five non-cancer mucosal tissue samples, using cDNA microarrays." (PMID 24386239, 2013).
esophageal cancer (4 papers, 2021 to 2024). A primary or metastatic malignant neoplasm involving the esophagus. "For example, the transcriptional expression of ARHGAP11A was significantly elevated relative to normal tissues in esophageal carcinoma (ESCA) and stomach adenocarcinoma (STAD)." (PMID 34733886, 2021). "A GEO-based prognostic model consisting of six gene products (ARHGAP11A, H1.4, HMGB3, LRIG1, PRR11, and COL4A1) has been shown to be a reliable predictor of esophageal cancer." (PMID 39062899, 2024). "A prognostic model consisting of six gene products (HMGB3, ARHGAP11A, H1.4, LRIG1, PRR11, and COL4A1) is a reliable predictor of esophageal cancer." (PMID 39062899, 2024).
lung carcinoma (3 papers, 2013 to 2021). "The results showed that CCNE1, E2F1, ARHGAP11A, RUNX1T1 and FES were significantly associated with patient survival in lung cancer (n = 1925)." (PMID 33613291, 2021).
pancreatic cancer (3 papers, 2013 to 2024). "Although the mechanism of action of ARHGAP5 and ARHGAP11A in pancreatic cancer is unclear, some oncogenic mechanisms have been identified in other tumors." (PMID 38783033, 2024). "Whether ARHGAP11A can promote the progression of pancreatic cancer by modulating the tumor immune microenvironment is a direction worth exploring in the future." (PMID 38783033, 2024). "Three potential prognostic markers (ARHGAP5, ARHGAP11A, and ARHGAP12) for pancreatic cancer were identified." (PMID 38783033, 2024).